FOXO6 (forkhead box O6)
Diseases named in the same sentence as FOXO6 in open-access papers (continued):
Sharing a sentence is not in itself a finding about the gene and the disease.
breast tumors (2 papers, 2018 to 2020). "Surprisingly, we found that FOXO6 was often highly overexpressed in human breast tumours and cell lines at both the mRNA and protein levels." (PMID 29484124, 2018). "However, this approach allowed us to highlight that the high expression of FOXO6 was a marker of poor prognostic in our subpopulation of breast tumors HR- and ERBB2- (triple negative breast tumors) (p = 0.0053)." (PMID 29484124, 2018). "FOXO6 overexpression was not a prognostic marker in our series of 527 breast tumors (data not shown)." (PMID 29484124, 2018). "The FOXO6 overexpression observed in human breast tumours and cell lines would therefore not be due to this molecular mechanism." (PMID 29484124, 2018). "The prognostic value of the FOXO6 expression in this subpopulation of breast tumors is therefore independent of biological parameters studied." (PMID 29484124, 2018). "However, we have not found any correlation between the expressions of FOXO6 and c-Myc in breast tumors (data not shown), strongly suggesting that the overexpression of FOXO6 would act on breast carcinogenesis via a specific mechanism independent of the transcriptional factor Myc." (PMID 29484124, 2018). "We confirmed that FOXO6, but not FOXO1, 3 or 4, was frequently overexpressed in breast cell lines (25%) and in breast tumours (26.9%)." (PMID 29484124, 2018).
cardiac hypertrophy (2 papers, 2023 to 2025). "The knockout and overexpression of FoxO6 in the heart attenuated and exacerbated cardiac hypertrophy and fibrosis, which was directly associated with myocardial contractile function." (PMID 37799807, 2023). "FoxO6 deficiency remarkably reduced the degree of cardiac hypertrophy." (PMID 37799807, 2023). "Based on analysis for a multitude of high‐throughput transcriptomic datasets derived from mouse HF samples, we here observed a significant downregulation of a lncRNA, forkhead box O6, opposite strand (Foxo6os) in cardiac hypertrophy models." (PMID 40548957, 2025). "The degree of cardiac hypertrophy was also obviously aggravated in Ang‐II‐treated FoxO6‐overexpressing mice." (PMID 37799807, 2023). "With Ad FoxO6 transfection and Ang‐II treatment, FoxO6 overexpression further exacerbated cardiac hypertrophy and increased the expression of β‐MHC, ANP, and TGF‐β1." (PMID 37799807, 2023). "FoxO6 cKO, similar to the effects of Ang‐II, significantly attenuated cardiac hypertrophy after TAC surgery, as evidenced by the ventricular wall thickness measured by ultrasound and the cross‐sectional area of CMs." (PMID 37799807, 2023). "FoxO6 cKO significantly inhibited cardiac hypertrophy and fibrotic remodeling and improved cardiac function, which was achieved by inhibiting the expression of Kif15." (PMID 37799807, 2023). "We also characterized the signaling pathways regulated by FoxO6 in cardiac hypertrophy." (PMID 37799807, 2023). "Among these five potentially critical factors, only FoxO6 protein levels also increased significantly with time after Ang‐II treatment, paralleled by raised levels of the indices of cardiac hypertrophy, specifically, myosin heavy chain β (β‐MHC) and atrial natriuretic peptide (ANP)." (PMID 37799807, 2023). "This study aimed to explore the role of FoxO6 in cardiac hypertrophy." (PMID 37799807, 2023). "In this study, we created a mouse model of pathological cardiac hypertrophy by angiotensin‐II (Ang‐II) treatment and transverse aortic constriction (TAC) to explore the function of FoxO6 in the modulation of cardiac function and remodeling." (PMID 37799807, 2023).
Hyperglycemia (2 papers, 2023 to 2024). An increased concentration of glucose in the blood. "Dephosphorylation at Thr26 and Ser184 sites in FoxO6 enhances its activity, consequently leading to increased levels of hyperglycemia." (PMID 38441531, 2024). "Our conclusions indicate that the upregulation of ApoC3 by FoxO6 promotes the development of hyperlipidemia, hyperglycemia, and hepatic steatosis in vivo, and in vitro." (PMID 38441531, 2024). "In this context, our investigation aimed to examine the relationship between age-related hepatic steatosis and hyperglycemia, alongside studying how FoxO6 regulates ApoC3 during hyperglycemic conditions in both liver tissues and cells." (PMID 38441531, 2024). "Furthermore, HFD-fed aged rats displayed increased vulnerability to lipid accumulation and hyperglycemia, potentially influenced by the activation of FoxO6, alterations in lipoprotein metabolism, and modulation of lipogenesis gene expression." (PMID 38441531, 2024). "However, it was observed that hyperglycemia induced lipid accumulation through the activation of FoxO6." (PMID 38441531, 2024). "Furthermore, in the context of hyperglycemia, hepatic expression and activation of FoxO6 significantly contribute to increased ApoC3 production, impairing plasma TG metabolism associated with aging in HFD-fed conditions." (PMID 38441531, 2024). "Additionally, inhibiting the upregulation of FOXO6 inhibits hyperglycemia-induced oxidative stress and apoptosis in RPECs, which is mediated by the downregulation of FOXO6 to activate the AKT/nuclear factor erythroid 2-related factor 2 (Nrf2) pathway." (PMID 37978169, 2023). "Our findings indicate that FoxO6 triggered ApoC3-driven lipid accumulation in the livers of aged rats on an HFD and in FoxO6-Tg, consequently leading to hepatic steatosis and hyperglycemia." (PMID 38441531, 2024).
liver cancer (2 papers, 2016 to 2017). An epithelial or non-epithelial malignant neoplasm that arises from the liver. "Furthermore, FOXO6 expression could be used as a biomarker for deterioration and prognosis of liver cancer." (PMID 28404958, 2017). "Furthermore, FOXO6 expression can be used as a biomarker for deterioration and prognosis of liver cancer, which may provide a novel treatment target for HCC therapy." (PMID 27227932, 2016).
lymph node metastasis (2 papers, 2016 to 2017). "FOXO6 overexpression was significantly associated with depth of invasion, lymph node metastasis and stage of disease." (PMID 28404958, 2017). "FOXO6 expression was increased in both prominent serosal invasion group and lymph node metastasis group." (PMID 28404958, 2017). "While larger tumor size, upper tumor site, prominent serosal invasion, lymph node metastasis and FOXO6 overexpression (all P < 0.05) were unfavourable predictors for RFS." (PMID 28404958, 2017). "The results revealed that tumor size, depth of invasion, lymph node metastasis and FOXO6 status (all P < 0.05) were independent factors that affected OS." (PMID 28404958, 2017). "Furthermore, in order to assess the significance of FOXO6 in prognosis, all the patients were divided into different subgroups basing on tumor size, depth of invasion, and lymph node metastasis." (PMID 28404958, 2017). "Moreover, FOXO6 over-expression was correlated with poor prognosis in patients subgroups stratified by tumor size, depth of invasion and lymph node metastasis." (PMID 28404958, 2017).
Obesity (2 papers, 2012 to 2022). Accumulation of substantial excess body fat. "Surprisingly, high-fat diet specifically reduces the expression of FoxO3a and FoxO6 suggesting that IR/IGF-1 → FoxO-mediated transcription is involved in the pathogenesis of obesity-associated cognitive impairment." (PMID 22654904, 2012). "Coincidentally, FoxO6 has been shown to be involved in the dietary obesity and type 2 diabetes of animals via insulin resistance." (PMID 35883386, 2022).
Axenfeld-Rieger syndrome (1 paper, 2018). Axenfeld-Rieger syndrome (ARS) is a generic term used to designate overlapping genetic disorders, in which the major physical condition is anterior segment dysgenesis of the eye. "Furthermore PITX2, a regulator of Hippo signaling is associated with Axenfeld-Rieger Syndrome causing a flattened midface and we show that PITX2 activates FoxO6 expression." (PMID 30286078, 2018).
cardiomyopathy (1 paper, 2023). A disease of the heart muscle or myocardium proper. "Conversely, FoxO6 overexpression aggravated the cardiomyopathy and heart dysfunction." (PMID 37799807, 2023).
colon cancer (1 paper, 2019). "FOXO6 is a transcription factor mostly found in the nucleus that has been recently linked to EMT as its silencing has been associated with reduced cell proliferation, migration and invasion in colon cancer cells, via the inhibition of PI3K/Akt/mTOR pathway." (PMID 31293614, 2019).
endotoxemia (1 paper, 2015). "To determine whether aging influences endotoxin-induced changes to FoxO6 associated with hepatic inflammation in young (6 month) and old (24 month) SD rats, we injected animals with LPS (2 mg/kg) to mimic endotoxemia and euthanized animals 12 h later." (PMID 26506521, 2015).
fibrosis (1 paper, 2023). the formation of excess fibrous connective tissue in an organ or tissue in a reparative or reactive process. "For the first time, we have elucidated that FoxO6 in CMs promotes pathological cardiac fibrosis induced by pressure overload largely by activating Kif15, which contributes to TGF‐β1 secretion." (PMID 37799807, 2023).
Hepatic steatosis (1 paper, 2024). Steatosis is a term used to denote lipid accumulation within hepatocytes. "This discovery unveils a potential novel molecular target for therapeutic strategies against hepatic steatosis during the aging process, offering insights into its molecular and cellular underpinnings, particularly its association with FoxO6-mediated ApoC3 upregulation." (PMID 38441531, 2024). "However, the intricate mechanisms underlying hepatic steatosis induced by elevated FoxO6 under hyperglycemic conditions remain intricate and require further elucidation." (PMID 38441531, 2024). "FoxO6, an identified factor, induces hyperlipidemia and hepatic steatosis during aging by activating hepatic lipoprotein secretion and lipogenesis leading to increased ApoC3 concentrations in the bloodstream." (PMID 38441531, 2024). "Taken together, our findings underscore the significance of FoxO6 in driving hyperlipidemia and hepatic steatosis specifically under hyperglycemic states by enhancing the expression of ApoC3 in aged rats." (PMID 38441531, 2024). "In conclusion, the upregulation of ApoC3 via FoxO6 activation leads to the induction of hyperlipidemia and hepatic steatosis in aged rats subjected to an HFD." (PMID 38441531, 2024). "The transcriptional activation of FoxO6 induced by both the HFD and high glucose levels resulted in hepatic steatosis by upregulating ApoC3 and genes associated with gluconeogenesis in aged rats and liver cell cultures." (PMID 38441531, 2024).
hyperlipidemia (1 paper, 2024). "Conversely, the absence of FoxO6 attenuated the expression of genes involved in lipogenesis, resulting in diminished hepatic lipid accumulation and mitigated hyperlipidemia in murine models." (PMID 38441531, 2024).
hypertriglyceridemia (1 paper, 2022). A laboratory test result indicating elevated triglyceride concentration in the blood. "Characterization of FoxO6 as an integrator of hepatic insulin signaling with TG-rich VLDL (VLDL-TG) production in the liver provides important insights into the mechanism of hypertriglyceridemia." (PMID 36296646, 2022). "Instead, downregulation of FoxO6 suppresses expression of MTP, leading to amelioration of hypertriglyceridemia." (PMID 36296646, 2022).
Impaired glucose tolerance (1 paper, 2013). An abnormal resistance to glucose, i.e., a reduction in the ability to maintain glucose levels in the blood stream within normal limits following oral or intravenous administration of glucose. "Overexpression of FoxO1 or FoxO6 in mouse liver causes elevated fasting blood glucose levels and impaired glucose tolerance." (PMID 24015318, 2013).
melanoma (1 paper, 2021). A malignant, usually aggressive tumor composed of atypical, neoplastic melanocytes. "During photoaging, the biological role of FoxO6 was found to play a role in melanogenesis in the B16F10 murine melanoma cell line." (PMID 34082382, 2021).
Myocardial fibrosis (1 paper, 2023). "In addition, significant expansion of LV volume, significant reduction of cardiac systolic function, and severe myocardial fibrosis suggest that FoxO6 overexpression plays a critical role in promoting HF." (PMID 37799807, 2023).
nasopharyngeal carcinoma (1 paper, 2023). A carcinoma arising from the nasopharyngeal epithelium. "LncRNA HOXC-AS1 promotes nasopharyngeal carcinoma progression by sponging miR-4651 to upregulate FOXO6." (PMID 37592311, 2023).
pancreatic cancer (1 paper, 2018). "Two of the transcripts, FOXA1 (known for its upregulation and pro-metastatic action in pancreatic cancer) and the putative tumor suppressor FOXO6, showed metarrestin exposure-dependent expression changes in KPC tumors and in cultured mouse and human pancreatic cancer cell lines." (PMID 30306263, 2018).
cancer (20 papers, 2015 to 2024). A tumor composed of atypical neoplastic, often pleomorphic cells that invade other tissues. "Elevated FOXO6 has indeed been associated with stimulating proliferation and progression in several cancers." (PMID 39499086, 2024). "Macropinocytosis in cancer has been reported to aid nutrient uptake; the role of FOXO6 in linking GSC state transitions with metabolism will therefore be an interesting avenue for further exploration." (PMID 39499086, 2024). "Previous studies on cancer or other disease model demonstrated that FoxO6 affects cell fate transition through regulation of glucose metabolism, autophagy and cell cycle and is associated with muscle differentiation." (PMID 34212295, 2021). "In mammalians, the Foxo subfamily includes four genes of forkhead box-O transcription factors (Foxos), Foxo1, Foxo3, Foxo4, and Foxo6 that play a key role in cancer." (PMID 35178394, 2021). "Surprisingly, very heterogeneous FOXO6 expression was observed in the various cancer tissues examined." (PMID 29484124, 2018). "Several reports found that overexpression of FOXO6 in cancer cells play an important role in tumor progression." (PMID 28404958, 2017). "The results of RT-PCR showed that the expression of FOXO6 mRNA in HCC tissue increased significantly in comparison with adjacent cancer tissue and normal tissue (both P <0.05)." (PMID 27227932, 2016). "The expression of FOXO6 in adjacent cancer tissue was upregulated slightly in comparison with normal tissue." (PMID 27227932, 2016). "In HCC tissue and adjacent cancer tissue, patients with high FOXO6 expression had a significantly elevated ROS level compared with those with low FOXO6 expression (both P <0.05)." (PMID 27227932, 2016). "The results also found that the expression of FOXO6 in HCC tissue was higher than that in adjacent cancer tissue and normal tissue." (PMID 27227932, 2016). "The results of Western blot demonstrated that the protein expression of FOXO6 in HCC tissue significantly upregulated in comparison with adjacent cancer tissue and normal tissue." (PMID 27227932, 2016). "Several proteins involved in cancer pathways had mutations in more than one patient, the most common being MUC4, GOLGA6L2, DSPP, FOXO6 and HLA-DRB1." (PMID 25605237, 2015). "Indeed, in several cancers, FOXO6 is elevated and has oncogenic roles, triggering increased proliferation and progression." (PMID 39499086, 2024). "It thus appears worthwhile to explore if FOXO6 inhibits Wnt signaling in human cancers." (PMID 37011861, 2023). "Here, we evaluated the expression, prognostic value, mutation, methylation, and clinical features of four FOXO family genes (FOXO1, FOXO3, FOXO4, and FOXO6) in 33 types of cancers based on the Cancer Genome Atlas (TCGA) and Genotype Tissue Expression (GTEx) databases." (PMID 36555288, 2022). "FOXO6 gene would therefore be involved in various cancer types." (PMID 29484124, 2018). "FOXOs, comprising FOXO1, FOXO3, FOXO4, and FOXO6, are the focus of cancer research recently." (PMID 30046342, 2018). "In general, FOXO6 overexpression promoting tumor progression indicates that FOXO6 could serve as a potential target in cancer therapy." (PMID 28404958, 2017). "Moreover, we evaluated the effect of invasiveness on the prognosis of FOXO6 expression in the way of taking MMP-9 as a marker for invasive potential of cancer cells." (PMID 28404958, 2017). "The expression of FOXO6 in adjacent cancer tissue was weakly positive." (PMID 27227932, 2016). "Therefore, using erlotinib to inhibitEGFR to kill the cancer cells increases the activity of FOXO6, which in turn promotesthe survival of some of the cells by activating the SOX2 gene." (PMID 25686219, 2015). "The total deleterious mutation percentage showed no mutation of the FOXO6 gene in pan-cancer." (PMID 36555288, 2022).
cancer (continued). "The FOXO transcription factor family contains four highly relevant members, namely, FOXO1, FOXO3a, FOXO4, and FOXO6, which are direct downstream targets of AKT and play important roles in cancer progression." (PMID 34183647, 2021). "In addition, members of the FOXO family, such as FOXO1, FOXO3, FOXO4, and FOXO6, have been found to participate in various physiological responses, such as DNA damage, caloric restriction and oxidative stress, and play crucial roles in cancer initiation, progression, and chemo‐resistance." (PMID 32368828, 2020). "Although this study demonstrates that miR-127 also downregulates other genes that are overexpressed in cancer, such as FOXO6, SOX11, SOX12, and FASN, it provides the first example that targeting NANOS1 could be a potential cancer treatment strategy." (PMID 36012673, 2022).